ZNF670 (zinc finger protein 670)
Description:
May be involved in transcriptional regulation.
Synonyms: MGC12466
Tractability: PROTAC: ubiquitination databases record sites on it.
Gene: Protein-coding gene on chromosome 1 (247,034,637 to 247,078,811, reverse strand). Ensembl gene ENSG00000277462.
Subcellular location: Nucleus
Subcellular location (Human Protein Atlas): Nucleoplasm; Cytosol
Pathways (Reactome):
Gene expression (Transcription): Generic Transcription Pathway
Gene Ontology:
Molecular function: protein binding; DNA-binding transcription factor activity, RNA polymerase II-specific; RNA polymerase II cis-regulatory region sequence-specific DNA binding
Biological process: lipid metabolic process; regulation of transcription by RNA polymerase II; regulation of DNA-templated transcription
Cellular component: nucleus
Genetic constraint (gnomAD): Loss-of-function variants: 7 observed, 11.46 expected, observed/expected ratio (o/e) 0.61, 90% interval 0.35 to 1.15. The upper end of that interval is the gene's LOEUF score, 1.15, which puts it in group 5 of 6, group 1 being the genes least tolerant of losing a copy. Missense variants: 444 observed, 481.07 expected, observed/expected ratio (o/e) 0.92, 90% interval 0.85 to 1. Synonymous variants: 136 observed, 161.44 expected, observed/expected ratio (o/e) 0.84, 90% interval 0.73 to 0.97.
Homologues: Orthologues: chimpanzee ZNF670 (99% identical), macaque ZNF670 (98% identical). Paralogues in human: ZNF627 (62% identical), ZNF136 (60% identical), ZNF625 (50% identical), ZNF426 (45% identical), ZNF287 (44% identical), ZNF527 (43% identical), ZNF214 (43% identical), ZNF530 (42% identical), ZKSCAN7 (41% identical), ZNF34 (41% identical), ZNF333 (41% identical), ZNF17 (40% identical), and 38 more.